SERPING1 (serpin family G member 1)
Description:
Serine protease inhibitor, which acrs as a regulator of the classical complement pathway. Forms a proteolytically inactive stoichiometric complex with the C1r or C1s proteases. May also regulate blood coagulation, fibrinolysis and the generation of kinins. Very efficient inhibitor of FXIIa. Inhibits chymotrypsin and kallikrein.
Synonyms: C1Inh; C1IN; C1NH; C1-INH; HAE1; HAE2
Tractability: Antibody: UniProt places it where antibodies can reach, with high confidence; its Gene Ontology location is reachable by antibodies, with high confidence; UniProt predicts a signal peptide or a membrane-spanning region. PROTAC: its protein half-life has been measured. Other modalities: an approved drug acts on it.
Gene: Protein-coding gene on chromosome 11 (57,597,387 to 57,619,246, forward strand). Ensembl gene ENSG00000149131.
Subcellular location: Secreted
Pathways (Reactome):
Hemostasis: Platelet degranulation; Regulation of clotting cascade
Immune System: Regulation of Complement cascade; Regulation of FXIIa and plasma kallikrein activity
Disease: Defective SERPING1 causes hereditary angioedema
Gene Ontology:
Molecular function: protein binding; serine-type endopeptidase inhibitor activity
Biological process: negative regulation of complement activation, lectin pathway; blood circulation
Cellular component: blood microparticle; extracellular exosome; extracellular matrix; extracellular region; endoplasmic reticulum lumen; platelet alpha granule lumen
Genetic constraint (gnomAD): Loss-of-function variants: 5 observed, 37.84 expected, observed/expected ratio (o/e) 0.13, 90% interval 0.068 to 0.28. The upper end of that interval is the gene's LOEUF score, 0.28, which puts it in group 1 of 6, group 1 being the genes least tolerant of losing a copy. Missense variants: 505 observed, 633.13 expected, observed/expected ratio (o/e) 0.8, 90% interval 0.74 to 0.86. Synonymous variants: 225 observed, 249.65 expected, observed/expected ratio (o/e) 0.9, 90% interval 0.81 to 1.01.
Gene-disease validity (ClinGen):
ClinGen rates the evidence that SERPING1 causes each of these diseases.
hereditary angioedema with C1Inh deficiency (autosomal dominant): Definitive. Forms of hereditary angioedema that occur due to mutations in the gene for complement C1 inhibitor protein.
Homologues: Orthologues: chimpanzee SERPING1 (98% identical), macaque SERPING1 (93% identical), dog SERPING1 (70% identical), rat Serping1 (69% identical), mouse Serping1 (69% identical), pig SERPING1 (68% identical), guinea pig SERPING1 (61% identical), rabbit SERPING1 (56% identical), zebrafish serping1 (29% identical). Paralogues in human: SERPINF2 (24% identical), SERPINA3 (21% identical), SERPINF1 (20% identical), SERPINA5 (20% identical), SERPINB9 (20% identical), SERPINB4 (20% identical), SERPINB8 (20% identical), SERPINB3 (20% identical), SERPINA1 (19% identical), SERPINB1 (19% identical), SERPINB10 (19% identical), SERPINA4 (19% identical), and 24 more.
Diseases named in the same sentence as SERPING1 in open-access papers:
SERPING1 is named in the same sentence as 257 diseases in open-access papers, as found by Europe PMC text mining. Sharing a sentence is not in itself a finding about the gene and the disease. The quoted sentences say what the papers report.
hereditary angioedema (357 papers, 2005 to 2026). Hereditary angioedema (HAE) is a genetic disease characterized by the occurrence of transitory and recurrent subcutaneous and/or submucosal edemas resulting in swelling and/or abdominal pain. "Dysregulation of SERPING1 has been associated with conditions such as hereditary angioedema and inflammatory diseases." (PMID 40377287, 2025). "While SERPING1 mutations have been extensively linked to type I and II Hereditary angioedema (HAE), its implications in oncology have remained relatively unexplored." (PMID 39962118, 2025). "Hereditary angioedema (HAE) is a rare autosomal-dominant disease that is caused by a deficiency (type I) or dysfunction (type II) of the C1 inhibitor (C1-INH) due to a mutation in the SERPING1 gene, which codes for C1-INH." (PMID 38978843, 2024). "As a member of the serpin family of protease inhibitors, previous studies have shown that SERPING1 is associated with cardiovascular aging and hereditary angioedema." (PMID 39835101, 2024). "Exon 5’s missense variants of the SERPING1 gene have been repeatedly described as the cause of hereditary angioedema." (PMID 38255179, 2023). "The HAE VCEP will start with an extension of the curation of variants in C1-INH (SERPING1), the gene responsible for Hereditary Angioedema due to C1-inhibitor deficiency (C1-INH-HAE; OMIM: 106100)." (PMID 38124188, 2023). "SERPING1 deficiency has been linked to the development of hereditary angioedema, sepsis, and pancreatic cancer." (PMID 35874629, 2022). "Individuals with hereditary angioedema (HAE) have an ongoing activation of the complement system due to mutations in the SERPING1 gene." (PMID 35344299, 2022). "In hereditary angioedema, SERPING1 deficiency leads to accumulation of excess BK, which in turn over-activates B1R." (PMID 39086962, 2022). "Hereditary angioedema (HAE) due to C1 esterase inhibitor (C1-INH) deficiency (C1-INH-HAE) is a rare—estimated prevalence is 1:10000 to 1:50000—, autosomal dominant disorder caused by mutation in SERPING1 gene and belongs to the bradykinin mediated angioedemas." (PMID 35787812, 2022). "c.1029+384A>G transition to human serpin family G member 1 (SERPING1) gene creates a donor splice site in intron 6 and causes ‘VariO:0504 inclusion of cryptic exon’ leading to hereditary angioedema (HAE) type I." (PMID 32951567, 2021). "Hereditary angioedema (HAE) is caused by a SERPING1 gene defect resulting in decreased (Type I) or dysfunctional (Type II) C1 esterase inhibitor (C1-INH)." (PMID 32514272, 2020). "We recently investigated the pathways of immunoreactive bradykinin (iBK) formation in fresh blood of normal volunteers and of patients with hereditary angioedema (HAE) due to C1 esterase inhibitor (C1-INH) deficiency (mutations of the SERPING1 gene)." (PMID 31133046, 2019). "Hereditary Angioedema (HAE) is a rare disease that is primarily caused by mutations in the SERPING1 gene." (PMID 29867566, 2018). "Hereditary angioedema (HAE) due to C1 inhibitor (C1-INH) deficiency is a rare autosomal dominant disease caused by mutations in the SERPING1 gene resulting in reduced levels (type I) or dysfunction (type II) of C1-INH." (PMID 30127805, 2018). "The hereditary angioedemas (HAEs) are usually caused by autosomal dominant inheritance of SERPING1 gene mutations." (PMID 27537564, 2016). "Deficiency of C1-INH due to mutations in the SERPING1 gene causes Hereditary Angioedema (HAE) types I and II." (PMID 25053016, 2014). "SERPING1 (also known as C1-inhibitor) is particularly interesting, since several mutations of this gene are involved in the development of hereditary angioedema (MIM&606860,)." (PMID 16129025, 2005). "Other group A proteins mapped to pathways of defective factor XII and defective SERPING1, which cause hereditary angioedema, CD22 (receptor predominantly restricted to B cells)-mediated BCR (B-cell receptors) regulation, and the recycling of bile acids and salts." (PMID 39057787, 2024).
hereditary angioedema (continued). "Hereditary angioedema due to deficiency (type 1) or defective function (type 2) of C1 inhibitor protein is caused by loss of function mutations in the SERPING1 gene which may be autosomal dominantly inherited or occur through de-novo gene mutation." (PMID 39006039, 2024). "Furthermore, we evaluated a disease-relevant deletion, the SERPING1 (c.351delC) mutation, linked to the development of hereditary angioedema in patients." (PMID 36302757, 2022). "Hereditary angioedema with C1 Inhibitor deficiency (C1-INH-HAE) is caused by a constellation of variants of the SERPING1 gene (n = 809; 1,494 pedigrees), accounting for 86.8% of HAE families, showing a pronounced mutagenic liability of SERPING1 and pertaining to 5.6% de novo variants." (PMID 35958943, 2022). "Existing evidence indicates that modifier genes could change the phenotypic outcome of the causal SERPING1 variant and thus explain the expression variability of hereditary angioedema due to C1-inhibitor deficiency (C1-INH-HAE)." (PMID 35873600, 2022). "Mutations in SERPING1 cause hereditary angioedema in humans." (PMID 30918657, 2019). "Hereditary angioedema (HAE) is rare disorder caused by mutations of the SERPING1 or F12 genes." (PMID 27965672, 2016). "Hereditary angioedema (HAE) is a rare disorder predominantly caused by reduced levels or activity of C1 esterase inhibitor (C1INH) due to a mutation in the genes coding for C1INH (SERPING1)." (PMID 24013493, 2013). "PURPOSE: Hereditary angioedema due to C1-inhibitor deficiency (HAE-C1INH) is caused by heterozygous pathogenic variants in the SERPING1 gene." (PMID 41896320, 2026). "To enhance the diagnostic accuracy of hereditary angioedema (HAE) caused by SERPING1 mutations, we recommend adhering to the general testing algorithm outlined by the World Allergy Organization and the European Academy of Allergy and Clinical Immunology." (PMID 40313637, 2025). "Hereditary angioedema (HAE) is an autosomal dominant (AD) disorder caused by defects in the SERPING1 gene encoding C1-esterase inhibitor (C1-INH)." (PMID 39823539, 2025). "C1-inhibitor (C1INH) deficiency due to a mutation in the SERPING1 gene is the most common cause of hereditary angioedema (HAE)." (PMID 39399485, 2024). "Hereditary angioedema due to C1 inhibitor deficiency (HAE-C1INH) is an autosomal dominant genetic disease caused by mutations in the SERPING1 gene that encodes for C1 esterase inhibitor (C1INH)." (PMID 38773490, 2024). "The most common reason for C1INH deficiency is hereditary angioedema (HAE-C1INH), a rare genetic disease caused by a mutation in the SERPING1 gene." (PMID 38799421, 2024). "Hereditary Angioedema due to C1-inhibitor deficiency (C1-INH-HAE) is caused by pathogenic variants in the SERPING1 gene, located on chromosome 11q12-q13.1." (PMID 38124188, 2023). "Hereditary Angioedema (HAE) with C1-inhibitor (C1-INH) deficiency is caused by heterozygous mutations in the SERPING1 gene encoding C1-INH." (PMID 38124188, 2023). "The most common form of hereditary angioedema, C1‐INH‐HAE, is primarily caused by alterations in the SERPING1 gene." (PMID 33560480, 2021). "Hereditary angioedema (HAE) is a rare autosomal dominant genetic condition with inherited deficiency or dysfunction of C1 inhibitor due to a mutation in the SERPING1 gene." (PMID 34924008, 2021). "Hereditary angioedema (HAE) resulting from the mutation of the SERPING1 gene encoding the C1-INH protein (C1-INH-HAE) has two types, both exhibiting autosomal dominant inheritance." (PMID 32431708, 2020). "This syndrome is a clinical feature of patients with hereditary angioedema (HAE), in which, a mutation in the SERPING1 gene leads to a reduced expression of C1 protein that lessens its function as a bradykinin regulator." (PMID 32983137, 2020). "Hereditary angioedema with C1 inhibitor deficiency (C1-INH-HAE) is a rare, chronic disease caused by SERPING1 gene mutations." (PMID 31360439, 2019).
hereditary angioedema (continued). "Hereditary angioedema (HAE) is a rare autosomal dominant disorder caused by mutations of the SERPING1 or the Factor 12 genes." (PMID 27965672, 2016). "Hereditary angioedema (HAE) is an autosomal dominant genetic disorder caused by mutations in the C1 esterase inhibitor gene, SERPING1, leading to overproduction of bradykinin and debilitating swelling attacks." (PMID 40313637, 2025). "Hereditary angioedema (HAE) is a rare genetic disease, caused by a deficiency (type 1) or defective function (type 2) of the C1 inhibitor (C1INH; HAE-C1INH), due to pathogenic variants in the SERPING1 gene." (PMID 40438097, 2025). "Hereditary angioedema (HAE) is a rare, life-threatening autosomal dominant genetic disease, most commonly caused by mutations in the SERPING1 gene on chromosome 11q." (PMID 40313637, 2025). "Most cases of bradykinin‐driven hereditary angioedema (HAE) are due to defects in the SERPING1 gene leading to low serum levels and decreased function of C1 inhibitor in HAE‐C1INH type 1 and type 2, respectively." (PMID 38415974, 2024). "Hereditary angioedema due to C1-esterase inhibitor deficiency (C1-INH-HAE) is caused by reduced synthesis (C1-INH-HAE type I) or the production of an unfunctional C1-INH protein (C1-INH-HAE type II) due to mutations in the C1-INH gene (SERPING1)." (PMID 36851094, 2023). "Its encoding gene, SERPING1, can be affected by more than 800 variants leading to uncontrolled pathological BK release responsible of subsequent increased endothelial permeability and a clinical phenotype of hereditary angioedema (HAE)." (PMID 36156118, 2022). "On the other hand, SERPING1 is an inhibitor of factor XII and mutations in SERPING1 cause hereditary angioedema." (PMID 35684129, 2022). "Hereditary angioedema (HAE) is a rare disease caused by mutations in the SERPING1 gene." (PMID 36172291, 2022). "Hereditary Angioedema (HAE) is a rare genetic disease generally caused by deficiency or mutations in the C1-inhibitor gene, SERPING1, a member of the Serpin family." (PMID 34354123, 2021). "Reduced levels of C1 esterase inhibitor (C1-INH) may be due to genetic defects in the SERPING1 gene (hereditary angioedema—HAE) or acquired deficiency (acquired angioedema—AAE) often associated with lymphoproliferative disorders." (PMID 32163480, 2020). "Hereditary angioedema with C1 inhibitor deficiency (C1-INH-HAE) is caused by mutations in the SERPING1 gene (OMIM 106100), the C1-INH encoding gene." (PMID 32962702, 2020). "In hereditary angioedema (HAE), a mutation in the SERPING1 gene causes either deficiency or dysfunctional C1-esterase inhibitor (C1-INH), resulting in activation of contact-kinin system and increased production of bradykinin leading to episodic angioedema." (PMID 32514273, 2020). "Whereas types I and II Hereditary angioedema result from SERPING1 mutations and are associated with low C1 esterase inhibitor level or function; HAE-nC1 INH, as its name implies, has normal C1 esterase inhibitor studies and appears to be formed by a heterogenous group." (PMID 31749860, 2019). "Hereditary angioedema with C1 inhibitor deficiency (C1-INH-HAE) is a rare inherited disease, due to mutations of the SERPING1 gene." (PMID 29866145, 2018). "SERPING1 is also a risk gene for hereditary angioedema (HAE)." (PMID 30379966, 2018). "Hereditary angioedema (HAE) is caused by mutations in Serping1, which encodes C1-INH, a serine protease inhibitor that regulates activation of the classical and lectin (and possibly the alternative) complement pathways and the contact activation pathway of the coagulation system." (PMID 25670937, 2014). "The kinins (primarily bradykinin, BK) represent the mediators responsible for local increase of vascular permeability in hereditary angioedema (HAE), HAE I-II associated with alterations of the SERPING1 gene and HAE with normal C1-Inhibitor function (HAE-nC1INH)." (PMID 23940538, 2013).
hereditary angioedema (continued). "Hereditary angioedema (HAE) is an autosomal dominant disorder (mostly hereditary, although 25% of cases are sporadic), which is caused by the deficiency or dysfunction of the serpin C1 esterase inhibitor (C1-INH, gene SERPING1)—known as Type 1 HAE (~85% of cases) and Type 2 HAE, respectively." (PMID 38339082, 2024). "Hereditary angioedema due to C1 inhibitor deficiency (HAE-C1-INH) is an autosomal dominant disease with an estimated prevalence of 1:50,000 and is caused by mutations in the SERPING1 gene, which codes for C1 esterase inhibitor (a serine protease inhibitor)." (PMID 37112764, 2023). "Hereditary angioedema (HAE) arising from mutations in the SERPING1 gene encoding C1-INH is a rare autosomal dominant disease that can lead to life-threatening edemas, and the treatment with recombinant C1-INH is approved for acute and prophylactic management." (PMID 37426666, 2023). "Top Reactome pathways enriched for the 65 unique proteins identified in the PSCs were pathways regulating striated muscle contraction, ARMS-mediated activation, defective PGM1, Factor XII, and SERPING1 casing hereditary angioedema, and in collagen degradation among others." (PMID 36002889, 2022). "Hereditary angioedema (HAE) types I and II (HAE-1/2) refer to an autosomal dominant and potentially life-threatening disease caused by mutations of the gene “serpin family G member 1” (SERPING1) encoding the C1-inhibitor (C1–INH)." (PMID 33643518, 2021). "Hereditary angioedema due to C1-INH deficiency (C1-INH-HAE), the prototype of primary angioedema, is an autosomal dominant disease caused by deleterious mutations in the SERPING1 gene, leading to quantitative and/or functional C1 inhibitor (C1-INH) deficiency." (PMID 33114181, 2020). "Decreased expression or function of C1 inhibitor (C1-INH, product of the SERPING1 gene) is the molecular basis of type 1 and 2 hereditary angioedema (HAE-1, HAE-2), respectively, with ensuing uncontrolled consumption of HK and massive BK generation during attacks." (PMID 30333824, 2018). "Hereditary angioedema with normal C1-inhibitor (nC1-INH HAE) is believed not to be caused by SERPING1 mutations." (PMID 26154504, 2015). "Hereditary angioedema with C1 inhibitor deficiency (C1-INH-HAE) is a rare autosomal dominant disease with an uncertain prevalence estimated to be 1: 50 000 and is caused by mutation in the SERPING1 gene." (PMID 26154504, 2015). "Mutations in SERPING1 cause hereditary angioedema, but there is no known phenotypic overlap with AMD such as had been established with atypical hemolytic uremic syndrome or glomerulonephritis arising in patients with mutations in CFH." (PMID 19169411, 2009). "Similarly, hereditary angioedema, a rare illness characterized by recurrent episodes of swelling in diverse body areas, can be brought on by mutations in SERPING1, the gene that codes for the C1 inhibitor." (PMID 39063029, 2024). "In hereditary angioedema (HAE), genetic defects in the C1-INH gene (Serine Protease Inhibitor Gene 1 present on the Long Arm of Chromosome 11 [11q]: SERPING1) can result in a deficient or dysfunctional protein (HAE Type I and II, respectively [HAE-C1INH])." (PMID 32514272, 2020). "Hereditary angioedema (HAE) is an autosomal dominant disease caused by C1-INH deficiency due to mutations in SERPING1 (C1-INH-HAE) in most of the cases, or by specific mutations in factor XII gene, F12 (F12-HAE)." (PMID 30847342, 2019). "Hereditary angioedema (HAE) is a rare autosomal dominant disease caused by deleterious mutations in SERPING1, leading to quantitative or functional C1-inhibitor deficiency (C1-INH-HAE)." (PMID 30847342, 2019). "Hereditary angioedema type I and II (HAE, #MIM106100), an autosomal dominant disorder, is caused by mutations in C1 inhibitor (C1INH, SERPING1)." (PMID 30633749, 2019). "SERPING1, a protease inhibitor approved by the FDA for the treatment of hereditary angioedema, serves as regulators for complement activation." (PMID 29262557, 2017).